FTO (FTO alpha-ketoglutarate dependent dioxygenase)
Diseases named in the same sentence as FTO in open-access papers (continued):
Sharing a sentence is not in itself a finding about the gene and the disease.
leukemia (continued). "In leukemia, FTO inhibition sensitizes leukemia cells to T-cell cytotoxicity and overcomes immune evasion." (PMID 38001065, 2023). "In primary leukemia, FTO increases the stability of a series of proliferation and survival mRNAs, for example B-cell lymphoma-2 (BCL-2) and tyrosine-protein kinase Mer (MERTK), and subsequently promotes protein synthesis." (PMID 37055798, 2023). "FTO expression was suppressed by R-2HG treatment in sensitive leukemia cells through downregulation of CEBPA transcription factor but not in resistant cells." (PMID 37161388, 2023). "As the first identified m6A demethylase, FTO has been shown to promote leukemia oncogene-mediated cell transformation as well as leukemogenesis." (PMID 37007137, 2023). "In vitro experiment results showed that FTO can promote cell proliferation/transformation, inhibit cell apoptosis, and significantly promote the occurrence of leukemia in vivo." (PMID 37007137, 2023). "FTO is largely enhanced in some leukaemia cells and promotes leukaemia progression through multiple signalling pathways." (PMID 36859310, 2023). "researchers have synthesized a hybrid FTO inhibitor by merging fragments from previously reported inhibitors with anti-leukemia activity." (PMID 36810281, 2023). "It attenuates aerobic glycolysis and downregulates the expression of FTO/LDHB/PFKP in leukemia cells." (PMID 35186927, 2022). "FB23–2 exhibited FTO-dependent anti-leukemia effects broadly and targeted the same signaling pathways as FB23." (PMID 36517820, 2022). "In contrast, FTO is also highly abundant in the cell cytoplasm and can mediate up to 40% m6A demethylation of total mRNA in certain leukemia cells." (PMID 35186927, 2022). "Mechanistically, R-2HG suppressed FTO activity and elevated the global m6A modification levels in R-2HG-sensitive leukemia cells." (PMID 35945194, 2022). "The oncogenic potential of FTO has also been demonstrated in leukemia and glioblastoma, both of which have high levels of FTO expression." (PMID 36295107, 2022). "In leukemia, FTO is preferentially inhibited by R-2-hydroxyglutarate (R-2HG), an oncometabolite produced by mutant IDH1/2 enzymes." (PMID 35350378, 2022). "For instance, the 2OG competitive inhibitor 2-hydroxyglutarate (R-2HG, compound 1) has been identified as an FTO inhibitor, which displayed anticancer activity in leukemia and glioma." (PMID 35628623, 2022). "High level of R-2HG expressed by mutant isocitrate dehydrogenase, was demonstrated to play important antitumor effect in glioma and leukemia cells by inhibiting FTO activity." (PMID 35186927, 2022). "pharmacological inhibition of FTO significantly suppressed leukemia stem/initiating cell self-renewal and sensitized leukemia cells to T cell cytotoxicity." (PMID 35002524, 2022). "R-2-hydroxyglutarate (R-2HG), an antimetabolite generated by mutant isocitrate dehydrogenase 1/2 (IDH1/2), can target FTO to exert an anti-leukemia effect." (PMID 35720276, 2022). "Further research confirmed that FTO suppressed all-trans retinoic acid (ATRA)-induced leukemia cell differentiation by reducing ASB2 and RARA expression." (PMID 35628623, 2022). "FTO suppression makes leukemia cells sensitive to T cell toxicity and overcomes hypomethylation induced immune evasion." (PMID 35590394, 2022). "It was reported that knocking down FTO or LDHB (lactate dehydrogenase B) inhibits R-2HG in leukemia cells." (PMID 35186927, 2022). "Yan and collaborators demonstrate that FTO-m6A axis deregulation induces response to tyrosine kinase inhibitor (TKI) treatment in leukemia cells." (PMID 35186927, 2022). "MA derivative FB23-2 is also identified as selective inhibitor of FTO, and performs anti-leukemia functions in mouse AML model." (PMID 35999621, 2022). "Gene deletion of FTO significantly attenuates leukemia stem cell/initiation cell self-renewal and reprogramming immune response by inhibiting the expression of immune checkpoint genes (especially LILRB4)." (PMID 35590394, 2022).
leukemia (continued). "In leukemia, inhibition of FTO attenuates the self-renewal of leukemia stem cells and suppresses immune checkpoint receptors, especially leukocyte immunoglobulin-like receptor B4 (LILRB4)." (PMID 35804965, 2022). "Rhein, the first naturally occurred FTO inhibitor, displays therapeutic efficacy in leukemia mice by competitively binding to the catalytic site of FTO." (PMID 35999621, 2022). "For example, 3-deazaadenosine inhibits METTL3/METTL14, CA4 (carbonic anhydrase member) induces WTAP degradation and suppresses colorectal cancer proliferation, and R-2-hydroxyglutarate (R-2HG) delays leukemia progression via inhibition of FTO." (PMID 35794625, 2022). "The m6A demethylase FTO was overexpressed in leukemia cells, which enhanced mRNA stability of proliferation/survival transcripts, increased protein synthesis and induced TKIs resistance." (PMID 35144642, 2022). "FTO inhibition sensitizes leukemia cells to T cell cytotoxicity and overcomes immune evasion induced by hypomethylating agents." (PMID 35296338, 2022). "R-2HG plays an important role in anti-leukemia activity by targeting FTO through various mechanisms." (PMID 35720276, 2022). "In leukemia, FTO promoted the proliferation of AML cells by reducing m6A levels at the 3′-UTR of Asb2 and 3′ and 5′-UTR of Rara, two mediators of hematopoiesis and differentiation, resulting in decreased ASB2 and RARA protein expression." (PMID 35350378, 2022). "In leukemia, researchers found that the development of resistance phenotype during tyrosine kinase inhibitor (TKI) treatment depended on the reduction of m6A detected by m6A dot-blotting due to FTO overexpression in leukemia cells." (PMID 34745970, 2021). "The demethylation activity of FTO is suppressed by R-2HG and plays critical oncogenic roles in leukemia through an FTO/m6A/MYC-CEBPA axis." (PMID 34272618, 2021). "A study by Liu’s group showed that tyrosine kinase inhibitor (TKI) therapy resistant phenotypes depend on FTO overexpression and in turn m6A reduction in leukemia cells." (PMID 33611339, 2021). "For example, R-2HG, an inhibitor of demethylase FTO, combined with chemotherapy drugs, was found to exert synergistic anticancer effects against leukemia and glioma in vivo and in vitro." (PMID 34359836, 2021). "The genetic depletion and pharmacological inhibition of FTO significantly inhibited the self-renewal of leukemia stem cells, and induced immune responses by inhibiting the expression of immune checkpoint genes." (PMID 34956201, 2021). "R-2HG also effectively suppresses aerobic glycolysis in IDH-wild-type leukemia cells by targeting the FTO/m6A/YTHDF2 signaling pathway to downregulate the expression of two critical glycolytic genes, PFKP and LDHB, which contributes to its antitumor effects." (PMID 34001273, 2021). "FTO inhibition sensitizes leukemia cells to T cell cytotoxicity and overcomes hypomethylating agent-induced immune evasion, indicating the broad potential of targeting FTO for cancer therapy." (PMID 34650918, 2021). "R-2HG, a specific small molecule inhibitor of FTO, displays anti-leukemia activity by suppressing FTO/m6A/MYC signaling." (PMID 34149801, 2021). "Overexpression of FTO has been observed in multiple human cancer and is generally recognized as an oncogene in various types of cancers, including leukemia, brain, breast, gastric, lung, and cervical cancer." (PMID 34378866, 2021). "For example, R-2-hydroxyglutarate (R-2HG), produced by mutant isocitrate dehydrogenase 1/2 enzymes, was recently found to be able to restrain leukemia cell proliferation and induced cell apoptosis by targeting FTO/m6A/MYC/CEBPA signaling." (PMID 33611339, 2021). "R-2-Hydroxyglutarate (R-2-HG) can also inhibit FTO activity, thereby increasing the m6A RNA modification in R-2HG-sensitive leukemia cells, reducing the stability of MYC/CEBPA transcripts, and leading to the inhibition of related pathways." (PMID 34858499, 2021).
leukemia (continued). "R-2HG, which was known as a metabolic product of mutant IDH1/2, was defined as an inhibitor of FTO and inhibited leukemia progression." (PMID 34345203, 2021). "Previous studies on FTO in cancer suggested that FTO plays a carcinogenic part in glioblastoma and leukemia." (PMID 34794452, 2021). "During treatment with TKI, the reduction of the overall m6A modification level mediated by FTO induces the drug-resistant phenotype of leukemia cells." (PMID 33926508, 2021). "Oppositely, FTO upregulation in leukemia showed more TKI tolerance via enhancing MERTK and BCL-2 stability." (PMID 34745970, 2021). "In glioblastoma and leukemia, FTO is overexpressed and promotes the occurrence and development of tumours." (PMID 34794452, 2021). "Here, we showed that SsD displayed broad and intrinsic anti-tumor activity in leukemia both in vivo and in vitro by targeting FTO and its downstream pathways." (PMID 33897884, 2021). "Previously, we showed that the developing resistant phenotypes during TKI therapy depend on m6A reduction resulting from FTO overexpression in leukemia cells." (PMID 33897884, 2021). "Accumulating studies recently have reported that FTO acts as an oncogene in various cancers such as glioblastoma, leukemia, melanoma, and lung cancer." (PMID 34277426, 2021). "In most cell lines, FTO is mainly localized in the nucleus and mediates approximately 5-10% of the total mRNA m6A demethylation, while in some leukemia cells, FTO mediates up to 40% of the total mRNA m6A demethylation." (PMID 33994853, 2021). "On the other hand, 2-HG attenuates aerobic glycolysis in leukemia by targeting the FTO/m6A/PFKP/LDHB axis." (PMID 34516556, 2021). "In tyrosine kinase inhibitor (TKI)-resistant leukemia cells, decreased m6A levels by FTO upregulation results in the overexpression of survival and proliferation-related genes." (PMID 33072775, 2020). "R-2HG can inhibit FTO activity and thus elevating m6A mRNA modification in R-2HG-sensitive leukemia cells, thereby generating anti-leukemia effects." (PMID 33015074, 2020). "FTO is also upregulated in multiple tyrosine kinase inhibitor (TKI)-resistant leukemia cells, resulting in demethylation and overexpression of a subset of survival genes." (PMID 32111216, 2020). "FB23–2 can inhibit the m6A demethylase FTO, and it has been confirmed in leukemia studies that the degree of m6A methylation is reduced after intraperitoneal injection of FTO." (PMID 31992337, 2020). "Vice versa, knockdown of FTO rendered resistant leukemia cells remarkably sensitive to TKI treatments." (PMID 33072775, 2020). "Regarding the biological mechanism, R-2HG was shown to inhibit FTO activity, thus increasing the m6A mRNA modification in R-2HG-sensitive leukemia cells, reducing the stability of MYC/CEBPA transcripts, and inhibiting the related pathways." (PMID 32398132, 2020). "R-2HG exhibits broad antiproliferative effects in high-FTO leukemia via targeting FTO/MYC/CEBPA signaling." (PMID 31921664, 2019). "Therapeutically, R-2-hydroxyglutarate inhibits the activity of FTO, thereby suppressing leukemia progression." (PMID 31722709, 2019). "Recently, an important study revealed that FTO expression is upregulated in IDH-mutant leukemia and plays an anti-tumor role through the FTO/m6A/MYC/CEBPA signaling pathway." (PMID 30810537, 2019). "Our findings demonstrate an intrinsic and inducible FTO-m6A axis as a novel marker characterizing the heterogeneous nature of leukemia cells, and a broad defense mechanism by which leukemia cells develop TKI-resistant phenotypes." (PMID 30297871, 2018). "Third, although larger clones in naïve leukemia display an intrinsic TKI tolerance due to relatively high FTO expression, this TKI tolerance appears to be relatively moderate if normalized to the colony sizes." (PMID 30297871, 2018). "Our analysis has identified the FTO-m6A axis as a bona fide defense mechanism enabling leukemia cells to survive through TKI selection." (PMID 30297871, 2018).
leukemia (continued). "By directly binding and restraining the demethylase activity of FTO, R-2HG promotes overall m6A modification in R-2HG-sensitive leukemia cells." (PMID 30149601, 2018). "As the first identified messenger RNA N6-methyladenosine (m6A) demethylase, FTO has been shown recently to play m6A-dependent roles in adipogenesis and tumorigenesis (especially in the development of leukemia and glioblastoma)." (PMID 30105001, 2018). "R-2HG binds directly to FTO protein and inhibits its m6A demethylase activity, resulting in a significant increase of global m6A abundance in R-2HG-sensitive leukemia cells, and the effects of R-2HG is FTO-dependent." (PMID 29686311, 2018). "First, intrinsic and ectopic FTO expression renders leukemia cells insensitive to TKI-induced lethality." (PMID 30297871, 2018). "Our current findings disclose that these genetically homogeneous leukemia cells, in terms of BCR/ABL, KIT or FLT3 mutations, are epigenetically heterogeneous and can be distinguished by overexpression of FTO and reduction of m6A methylation." (PMID 30297871, 2018). "Su and colleagues have elaborated that R-2-hydroxyglutarate (R-2HG) exhibits broad and variable anti-proliferation effects in leukemia and glioma since it increases global m6A RNA modification in the sensitive cells via suppressing FTO." (PMID 29587823, 2018). "Here we show that developing resistant phenotypes during tyrosine kinase inhibitor (TKI) therapy depends on m6A reduction resulting from FTO overexpression in leukemia cells." (PMID 30297871, 2018). "This FTO-m6A axis appears to be intrinsic, pre-existing in naïve leukemia cell populations, and also be inducible in response to TKI treatment." (PMID 30297871, 2018). "Collectively, these findings support that rewired signaling programs driven by FTO upregulation regulate leukemia cell fate upon exposure to TKIs." (PMID 30297871, 2018). "We also find that the anti-leukemia effect of the small-molecule FTO inhibitor FB23–2 is not due to FTO inhibition since it remains cytotoxic to FTO-deficient cells." (PMID 41279954, 2025). "We next assessed the role of FTO in T-ALL progression after leukemia onset." (PMID 40435251, 2025). "Additionally, one study revealed that R-2HG attenuated aerobic glycolysis in leukemia by targeting the FTO/m6A/PFKP/LDHB axis." (PMID 41373022, 2025). "Furthermore, the study uncovered that SsD can overcome FTO/m6A-mediated leukemia resistance to TKIs, making it a promising candidate for addressing drug resistance in AML therapy." (PMID 40823087, 2025). "Therefore, the FTO-m6A axis has emerged as a novel marker characterizing leukemia cell heterogeneity and a broad defense mechanism for its resistance to tyrosine kinase inhibitors (TKIs)." (PMID 40823087, 2025). "Previous studies reported that D-2HG could inhibit FTO, an α-KG-dependent dioxygenase, thereby increasing m6A RNA modification levels in leukemia cells." (PMID 39910592, 2025). "Like MA, SsD has shown the ability to overcome FTO/m6A‐mediated leukaemia resistance to TKI." (PMID 38545841, 2024). "In leukemia cells with nucleophosmin 1 (NPM1) mutations, FTO reduces m6A levels and enhances autophagy by upregulating the expression of TP53INP2 and promoting the LC3-ATG7 interaction, which is critical for the survival of NPM1-positive leukemia cells." (PMID 39468015, 2024). "This raises the question of whether CS2's primary mechanism in leukemia involves hDHODH or FTO inhibition." (PMID 39085650, 2024). "Therefore, IDH mutants and FTO inhibition possess potential therapeutic values for leukemia treatment by mediating m6A modifications on critical transcripts in leukemogenesis." (PMID 39497033, 2024). "FTO enhances leukemogenesis and leukemia oncogene-mediated cell transformation by reducing m6A levels on mRNA transcripts of targets such as ASB2 and RARA, thereby regulating their expression and inhibiting all-trans retinoic acid (ATRA)-induced differentiation of AML cells." (PMID 39295872, 2024).
leukemia (continued). "Although the oncogenic role of FTO has been reported in leukemia, the functional significance of FTO in some leukemic cells, such as the human erythroleukemic cell line K562, appears to be less essential, possibly due to a lower level of endogenous expression in these cells." (PMID 38268050, 2024). "Additionally, the FTO/m6A/myelocytomatosis oncogene (MYC)/(CCAAT/enhancer binding protein α) (CEBPA) signaling pathway plays a crucial role in leukemia." (PMID 39295872, 2024). "For instance, FB23-2 is an FTO inhibitor developed as a candidate drug for treating leukemia." (PMID 39497033, 2024). "Knockdown of FTO promoted apoptosis in both leukemia and LUSC." (PMID 39033180, 2024). "FTO has been shown to promote the progression of several tumors including leukemia and melanoma." (PMID 39033180, 2024). "Interestingly, leukemia cells with the upregulation of FTO are more sensitive to R-2HG by FTO-enhanced stability of MYC transcripts." (PMID 37055798, 2023). "Moreover, R-2-hydroxyglutarate (R-2HG) specifically abrogates the upregulation of LDHB gene expression through m6A eraser FTO demethylation and thereby suppresses glycolysis in leukemia, indicating a function for m6A in cancer metabolic pathways." (PMID 37055798, 2023). "Research reported that FTO decreased m6A modification and stabilized mRNA of c-Myc in leukemia cells, thereafter, we hypothesized that FTO-IT1 might regulated c-Myc expression to form a reciprocal feedback." (PMID 37840133, 2023). "FTO, one of the key demethylases, has been found to play an oncogenic role in leukemia 29 and oral squamous cell carcinoma 15, and may be a potential therapeutic target." (PMID 36263177, 2022). "A variety of leukemia cells highly express FTO in several subtypes of AML." (PMID 35720276, 2022). "In addition, the metabolite R-2HG caused by isocitrate dehydrogenase (IDH) mutation exerts anti-leukemic effects by inhibiting FTO/m6A/MYC/CEBPA signaling, providing a new target for clinical dosing in the treatment of leukemia." (PMID 36118041, 2022). "Among these, studies have shown that FTO plays the role of an oncogene in acute myeloid leukemia by regulating the level of m6A and promoting the occurrence and development of leukemia." (PMID 36506331, 2022). "In acute myeloid leukemia, m6A demethylases, FTO plays a key role in the development of leukemia." (PMID 35628460, 2022). "Importantly, R-2HG exhibited a potent anti-tumor effect against leukemia with high FTO expression by targeting FTO-m6A-MYC/CEBPA axis." (PMID 35859892, 2022). "In addition, FTO mediates the resistance to tyrosine kinase inhibitors (TKIs) in leukemia cells by regulating MERTK and BCL-2 through m6A demethylation." (PMID 35720276, 2022). "FTO was found to regulate the expression of PD-L1 in leukemia." (PMID 35590394, 2022). "Genetic depletion or pharmacological inhibition of FTO dramatically attenuates leukemia stem/initiating cell self-renewal and reprograms immune responses by suppressing the expression of immune checkpoint genes such as leukocyte immunoglobulin-like receptor B4 (LILRB4)." (PMID 35296338, 2022). "In human acute myeloid leukemia (AML), FTO promotes the occurrence of leukemia." (PMID 35022030, 2022). "FTO has been shown to be carcinogenic in both leukemia and glioblastoma." (PMID 35568876, 2022). "Furthermore, overexpression of FTO contributes to TKI-resistance in leukemia cells via stabilizing MERTK and BCL2 mRNA." (PMID 35999621, 2022). "Notably, a study showed that inhibition of FTO by CS1/CS2 dramatically attenuated leukemia stem/initiating cell self-renewal and reprogrammed immune response." (PMID 35211409, 2022). "R-2HG, as a metabolite produced by mutant isocitrate dehydrogenases (IDHs), can inhibit FTO activity to increase the accumulation of m6A modified m6A in MYC transcripts of sensitive leukemia cells, resulting in decreased stability of MYC mRNA and downregulation of MYC signaling pathway." (PMID 35590394, 2022).